Y_RNA (Y RNA )
Gene: Miscellaneous RNA gene on chromosome 6 (31,496,689 to 31,496,790, reverse strand). Ensembl gene ENSG00000201680.
Homologues: Orthologues: macaque Y_RNA (94% identical). Paralogues in human: Y_RNA (94% identical), Y_RNA (92% identical), RNY3 (91% identical), Y_RNA (91% identical), RNY3P1 (90% identical), Y_RNA (90% identical), Y_RNA (89% identical), Y_RNA (88% identical), RNY3P14 (87% identical), Y_RNA (87% identical), Y_RNA (86% identical), RNY3P11 (85% identical), and 99 more.